ACSS2 (acyl-CoA synthetase short chain family member 2)
Diseases named in the same sentence as ACSS2 in open-access papers (continued):
Sharing a sentence is not in itself a finding about the gene and the disease.
depression (2 papers, 2023 to 2024). "In chronic-restraint-stress-induced depression mice, neuronal ACSS2 knockdown by stereotaxic injection of adeno-associated virus in the hippocampus abolished SCFA-mediated improvements in depressive-like behaviors of mice, supporting that ACSS2 is required for SCFA-mediated antidepressant responses." (PMID 38939042, 2024). "ACSS2 insufficiency or deficiency can increase the risk of depression pathogenesis." (PMID 37914710, 2023). "In mice, mRNA and protein levels of ACSS2 in the hippocampus, along with the typical behavioral phenotypes of depression, were reduced in response to chronic restraint stress (CRS)-induced depressive-like behaviors, as assessed by the TST." (PMID 37914710, 2023). "This novel information has clinical implications for the prevention and treatment of human depression and other metabolic diseases by targeting ACSS2." (PMID 37914710, 2023). "To support it as an antidepressant effect target, we screened the ability of diverse hexoses, such as D-glucose, D-fructose and D-mannose, which are abundantly present in the ordinary diet of humans, to enhance ACSS2 expression in resisting depression." (PMID 37914710, 2023). "Moreover, SCFAs, as brain ACSS2 inducers, are further supported to be a promising agent to prevent depression." (PMID 38939042, 2024). "However, how ACSS2 is regulated in the development of depression remains unclear." (PMID 38939042, 2024). "In summary, brain SCFAs can activate ACSS2–PPARγ–TPH2 axis to play the antidepressive-like effects, and d-mannose is suggested to be an inducer of brain SCFAs in resisting depression." (PMID 38939042, 2024). "As we observed that SCFAs can trigger ACSS2–PPARγ–TPH2 axis, the discovery of novel inducers of brain SCFAs is extremely important for treating depression." (PMID 38939042, 2024).
metastatic tumors (2 papers, 2020 to 2024). "ACSS2 inhibitors currently in Phase I study for metastatic tumors (NCT04990739) or a transition state ACSS2 mimetic may be better suited for a full apoptotic restoration to prevent stroma-dependent protection." (PMID 38851813, 2024). "Our results also provided evidence that acetate promotes SNAI1 expression through ACSS2-mediated histone acetylation, implying that inhibition of ACSS2 may be an important strategy in the treatment of metastatic tumors." (PMID 32458971, 2020).
pancreatic ductal adenocarcinoma (2 papers, 2023 to 2024). An infiltrating adenocarcinoma that arises from the epithelial cells of the pancreas. "Here, we report that the acetate-activating enzyme acetyl-CoA short-chain synthase family member 2 (ACSS2) is a positive regulator of alkaliptosis in human pancreatic ductal adenocarcinoma (PDAC) cells." (PMID 36707625, 2023). "ACSS2 is up-regulated in human pancreatic ductal adenocarcinoma cell lines, and shRNA knockdown of ACSS2 inhibits cancer cell death while increasing cell cloning and the decreasing of intracellular pH, indicating that it is an active regulator for the pancreatic ductal adenocarcinoma treatment." (PMID 38586328, 2024).
pancreatic neuroendocrine neoplasm (2 papers, 2024 to 2025). A neoplasm with neuroendocrine differentiation that arises from the pancreas. "Knockdown of ACSS2 and treatment with ACSS2 inhibitor have been shown to inhibit the progression of pancreatic neuroendocrine neoplasms." (PMID 40097417, 2025).
renal fibrosis (2 papers, 2024 to 2025). A final common manifestation of a wide variety of chronic kidney diseases characterized by glomerulosclerosis and tubulointerstitial fibrosis. "To understand the role of ACSS2-mediated H3K9cr in renal fibrosis, we generated mice with genetic deletion of ACSS2 using the CRISPR/Cas9 knock-out system." (PMID 38615014, 2024). "Inhibition of acyl-CoA synthetase short chain family member 2 (ACSS2) suppresses H3 K9 crotonylation-mediated IL-1β expression, thereby alleviating IL-1β-dependent macrophage activation and tubular cell senescence, and consequently delaying renal fibrosis." (PMID 40478495, 2025). "This suggests that ACSS2 could serve as a potential therapeutic target for modulating H3 K9 crotonylation level and for attenuating renal fibrosis progression." (PMID 40478495, 2025). "It is possible that crotonylation levels of other residue, not only H3K9, might be regulated by ACSS2 and could possibly play roles in regulating IL-1b-mediated renal fibrosis." (PMID 38615014, 2024). "Furthermore, genetic and pharmacologic inhibition of ACSS2 both suppress H3K9cr-mediated IL-1β expression, which thereby alleviate IL-1β-dependent macrophage activation and tubular cell senescence to delay renal fibrosis." (PMID 38615014, 2024).
triple-negative breast carcinoma (2 papers, 2022 to 2024). An invasive breast carcinoma which is negative for expression of estrogen receptor (ER), progesterone receptor (PR), and human epidermal growth factor receptor 2 (HER2). "A high expression of ACSS2 was found in invasive ductal carcinoma, adenocarcinoma, and triple-negative breast cancer." (PMID 35740562, 2022). "Immunohistochemical analysis of tissue sections of human triple-negative breast cancer showed that patients with a high expression of ACSS2 had a lower overall survival, and there was a strong correlation between ACSS2 levels and disease progression." (PMID 35740562, 2022).
abdominal aortic aneurysm (1 paper, 2023). Enlargement and ballooning of the vessel that supplies arterial blood to the abdomen, pelvis and legs. "The interaction of microRNA (miRNA/miR)-15b with the ACSS2 gene is important for the development of abdominal aortic aneurysm (AAA)." (PMID 37889674, 2023).
AIDS (1 paper, 2021). A syndrome resulting from the acquired deficiency of cellular immunity caused by the human immunodeficiency virus (HIV). "Indeed, in an NHP model of HIV/AIDS (SIV-infected RMs), reactivation of latent HIV was observed after an increase in expression of the fatty acid metabolic enzyme ACSS2 (crotonyl-CoA–producing enzyme acyl-CoA synthetase short-chain family member 2), which induced histone lysine crotonylation." (PMID 34579195, 2021).
alcohol use disorder (1 paper, 2025). "We sacrificed mice following the final, 4-h drinking session and queried gene expression in male and female WT and Acss2 KO mice across the brain, focusing on regions implicated in alcohol use disorder." (PMID 39653249, 2025). "Our findings further emphasize the critical role of Acss2 in alcohol metabolism and related epigenetic, transcriptional and behavioral changes, which warrant further exploration of this pathway as a potential future therapeutic target in humans suffering from alcohol use disorder." (PMID 39653249, 2025).
bladder tumor (1 paper, 2018). "This experiment revealed elevated ACSS2 expression in bladder tumor tissue cores." (PMID 29568353, 2018).
brain injury (1 paper, 2023). Acute and chronic (see also brain INJURIES, CHRONIC) injuries to the brain, including the cerebral hemispheres, CEREBELLUM, and brain STEM. "Earlier studies in the brain demonstrated a predominant localization of Acss2 in the nuclei of neurons, astrocytes and oligodendrocytes, with greatly increased expression 24 h following traumatic brain injury." (PMID 36835088, 2023).
cervical tumor (1 paper, 2021). "The H-score of TMA samples showed that the expression of PDL1 and ACSS2 was significantly higher in cervical tumor (T) tissues than in non-tumor (N) tissues." (PMID 34206705, 2021).
colitis (1 paper, 2025). Inflammation of the colon. "Our results indicated a decrease of crotonate in plasma from IBD patients, and crotonate supplementation effectively alleviated experimental colitis via the ACSS2‐H4K12cr‐CLDN7 axis." (PMID 40650658, 2025). "Genetic or pharmacological inhibition of ACSS2 remarkably impaired intestinal barrier integrity and worsened colitis." (PMID 40650658, 2025). "In all, these results suggest the crucial role of ACSS2 in colitis progression through maintaining intestinal epithelial barrier integrity." (PMID 40650658, 2025). "To reveal the mechanism of how ACSS2 directly suppressed colitis progression, we performed RNA‐seq from control and ACSS2 knockdown NCM460 cells." (PMID 40650658, 2025). "Genetic or pharmacological inhibition of ACSS2 dramatically impairs mouse intestinal barrier integrity and exacerbates colitis." (PMID 40650658, 2025). "Moreover, we identified that TNF‐α destabilized ACSS2 mRNA by enhancing its m6A modification level, thereby aggravating colitis." (PMID 40650658, 2025). "In conclusion, crotonate alleviates colitis in an ACSS2 enzymatic‐dependent manner." (PMID 40650658, 2025). "Our study identifies a key regulator for protein crotonylation, ACSS2, which was downregulated in the inflamed intestinal epithelium and demonstrated a negative correlation with colitis progression." (PMID 40650658, 2025).
diabetes (1 paper, 2023). "Additionally, compared with the control group of mice, ACSS2 was indeed upregulated in both glomerulus and renal tubular tissues of diabetes mice." (PMID 37870960, 2023).
folate deficiency (1 paper, 2022). A nutritional condition produced by a deficiency of FOLIC ACID in the diet. "It suggested that folinic acid supplementation attenuated increased of the ACSS2 level by folate deficiency." (PMID 36743291, 2022). "Our data showed that Kcr was increased in the cranial neural tube of embryos with folate deficiency-induced NTDs compared with that in wild-type controls, suggesting that open NTDs involve the upregulation of ACSS2." (PMID 36743291, 2022). "We also found that folic acid supplementation attenuates ACSS2 induced by folate deficiency." (PMID 36743291, 2022). "Our findings suggest folate deficiency leads to the occurrence of NTDs by altering ACSS2." (PMID 36743291, 2022). "Therefore, our data indicate that folate deficiency contributes to the onset of NTDs by altering ACSS2 and demonstrate that Kcr may be a metabolic-sensitive protein modification." (PMID 36743291, 2022).
Glucose intolerance (1 paper, 2016). Glucose intolerance (GI) can be defined as dysglycemia that comprises both prediabetes and diabetes. "Interestingly, in a previous study investigating glucose-intolerance biomarkers in circulating white blood cells (WBCs) in ApoE3Leiden mice treated with high-fat diet, Acss2 gene expression was proposed to be an accurate diagnostic biomarker for glucose intolerance." (PMID 27483348, 2016).
head and neck squamous cell carcinoma (1 paper, 2025). A squamous cell carcinoma that arises from any of the following anatomic sites: lip and oral cavity, nasal cavity, paranasal sinuses, pharynx, larynx, and salivary glands. "To comprehensively investigate the impact of the ACSS2 gene on the proliferation, invasion, and migratory capabilities of head and neck squamous cell carcinoma (HNSCC) cells, in this study, we established stable shACSS2-transfected knockdown cell lines along with their corresponding NC cell lines." (PMID 40858538, 2025).
Hepatic fibrosis (1 paper, 2022). The presence of excessive fibrous connective tissue in the liver. "ACSS2 deficiency inhibits activity of lipid transporters and fatty acid oxidation genes, which then lowers dietary lipid absorption, reduces triglyceride content, and lessens hepatic fibrosis." (PMID 35456988, 2022).
leukemia (1 paper, 2024). A malignant (clonal) hematologic disorder, involving hematopoietic stem cells and characterized by the presence of primitive or atypical myeloid or lymphoid cells in the bone marrow and the blood. "Our data support the view ACSS2 expression in leukemia is aimed at processing exogenous acetate to support proliferative growth." (PMID 38851813, 2024). "Collectively, this study uncovers the leukemia-stroma phosphoproteome emphasizing a role for ACSS2 in mediating AML growth and drug resistance." (PMID 38851813, 2024). "Validating these findings, we show ACSS2 substrate, acetate, promotes leukemic proliferation, ACSS2 knockout in leukemia cells inhibits leukemic proliferation and ACSS2 knockout in the stroma impairs leukemic metabolic fitness." (PMID 38851813, 2024). "In contrast, KG1a, OCI-AML3 and K562 pre-exposed to HS-5 ACSS2-KO had a markedly diminished OCR (2.7-fold, 1.7-fold, and 1.5-fold, respectively) compared to leukemia cells pre-cultured with HS-5 ACSS2-WT." (PMID 38851813, 2024). "Quantitative phosphoproteomic probing of this effect further revealed a metabolic-enriched phosphoproteome including significant up-regulation of acetyl-coenzyme A synthetase (ACSS2, S30) in leukemia-stroma HDACi treated cocultures compared with untreated monocultures." (PMID 38851813, 2024). "Despite these variables, by modeling stroma protection of leukemia with HDACi, ACSS2 was identified as a pertinent protein in leukemia-stroma interactions and corroborates with previously reported studies on the metabolic effects of leukemia-stroma cellular interactions." (PMID 38851813, 2024). "Our findings show that leukemia pre-exposure to HS-5 WT enhanced OCR compared to leukemia monocultures (KG1a, OCI-AML3, and K562) but pre-exposure to HS-5 ACSS2-KO abolished this observed enhanced metabolic or “respiratory” state." (PMID 38851813, 2024). "The phosphoproteome screen indicated that the acetyl-CoA processing enzymes ACSS2 and ACACA might be metabolically supporting leukemia through stroma interactions." (PMID 38851813, 2024).
mastitis (1 paper, 2022). Inflammation of breast tissue during lactation or postpartum due to an obstructed duct or infection. "For instance, ACSS2 (acyl-CoA synthetase short-chain family member 2) is well known to affect mastitis resistance in dairy cows and plays a role in the activation of acetate for de novo fatty acid synthesis." (PMID 35723402, 2022). "Other noteworthy genes (RHPN2, ACSS2, RHOU, and KRT7) showing lower expression in cows with mastitis have critical roles in biological pathways, cellular process, fatty acid synthesis, and metabolism." (PMID 35723402, 2022).
muscular dystrophy (1 paper, 2025). Muscular dystrophy (MD) refers to a group of more than 30 genetic diseases characterized by progressive weakness and degeneration of the skeletal muscles that control movement. "Given the discovery of a muscular dystrophy associated with 3-hydroxy-3-methyl-glutaryl-coenzyme A reductase (HMGCR), a key enzyme in cholesterol synthesis, we studied Acss2 in mice and the orthologous gene AcCoA in flies." (PMID 40936396, 2025).
osteosarcoma (1 paper, 2022). A usually aggressive malignant bone-forming mesenchymal neoplasm, predominantly affecting adolescents and young adults. "ACSS2 could be a new potential biomarker for early diagnosis and subsequent treatment of osteosarcoma." (PMID 36119478, 2022). "Our findings revealed that the expression of ACSS2 was down-regulated in osteosarcoma cells." (PMID 36119478, 2022). "Our study showed that ACSS2 might play an essential role in the prognosis of osteosarcoma." (PMID 36119478, 2022). "Results showed that the expression levels of SLC7A7 and ACSS2 were significantly decreased in two osteosarcoma cell groups (U20S and 143B) compared with the osteoblast cell group (hFOB), whereas MYC was up-regulated in osteosarcoma groups." (PMID 36119478, 2022).
pancreatic neuroendocrine tumor (1 paper, 2025). Pancreatic endocrine tumor, also known as pancreatic neuroendocrine tumor (PNET), describes a group of endocrine tumors originating in the pancreas that are usually indolent and benign, but may have the potential to be malignant. "This study unveils that ACSS2‐driven acetate metabolism fuels histone pan‐acetylation in pancreatic neuroendocrine tumors (PNETs), remodeling the epigenetic landscape." (PMID 40791180, 2025).
presbycusis (1 paper, 2022). Bilateral hearing loss caused by progressive degeneration of cochlear structures and central auditory pathways, typically associated with the aging process. "In the GSE49543 data set, four genes (Ywhag, Mapre2, Fgf1, Acss2) were used to construct the prognostic model, and those four genes were significantly up-regulated in the rat model of presbycusis." (PMID 35463035, 2022). "However, there is no literature suggesting the relationship between Acss2 and presbycusis." (PMID 35463035, 2022).
prostate tumors (1 paper, 2022). "Immunohistochemical observation showed that ACSS2 expression was high in metastatic prostate tumors, but relatively low in the surrounding normal tissues, and the expression level of ACSS2 in metastatic prostate tissues was higher than that in primary tumor tissues." (PMID 35740562, 2022).
pulmonary arterial hypertension (1 paper, 2024). Pulmonary arterial hypertension (PAH) is a group of diseases characterized by mean pulmonary artery pressure >20 mmHg and elevated pulmonary arterial resistance leading to right heart failure. "The glycolysis genes (ACSS2, ALAS2, ALDH3A1, ADOC3, NT5E, and TALDO1) identified in this study play important roles in the development of pulmonary arterial hypertension, providing new evidence for the involvement of glycolysis in PAH." (PMID 38837574, 2024).
renal cell adenocarcinoma (1 paper, 2021). A carcinoma arising from the renal parenchyma. "In human renal cell adenocarcinoma cell lines, the expression of the snail family transcriptional repressor 1 (SNAI1) is promoted by ACSS2." (PMID 34572472, 2021).
wasting syndrome (1 paper, 2011). "Down-regulation of other genes involved in fatty acid and phospholipid metabolism such as acyl-CoA synthetase short-chain family member 2 might contribute to the wasting syndrome commonly observed in the infected mice after 6 months of infection." (PMID 21283804, 2011).